CD4 (CD4 molecule)
Diseases named in the same sentence as CD4 in open-access papers (continued):
Sharing a sentence is not in itself a finding about the gene and the disease.
tumor (continued). "We found that YPF increased the percentages of CD4+ T cells and macrophages in tumor microenvironment, and the cytotoxicity of CD4+ T cells by inducing M1 macrophage polarization." (PMID 31780946, 2019). "Meanwhile, change of CD4+ T cells in the local tumor were inconsistent across the enrolled patients." (PMID 31340866, 2019). "First, we observed significant reduction in CD4+ T cells in lymph nodes of all tumor bearing WT and Stat4−/− mice compared to non-tumor bearing mice." (PMID 32010142, 2019). "This was also shown to be important to optimize CD4+ T cell help to cytotoxic CD8+ cells as CCR5 ligands can improve the anti-tumor response." (PMID 31379821, 2019). "T cell depletion and T cell transfer experiments demonstrated that anti-CD20 treatment leads to the development of a potent and specific memory CD4+ T cell response against CD20+ tumor cells." (PMID 31494742, 2019). "Conversely, we observed a significant decrease in the percentage of tumor infiltrating Foxp3+ Treg cells among CD4+ population in anti-4-1BB/anti-CD73-treated mice, compared with anti-4-1BB-treated mice alone." (PMID 30635578, 2019). "Similar effects were also seen for the CD8 T cell subset, whereas DCVacc/VSV‐GP combination treatment showed the strongest effect on the tumor‐infiltrating CD4 T cells." (PMID 30972741, 2019). "No significant changes in the expression of CD28 or NKG2D was observed on CD4 T cells in tumor draining LN." (PMID 31446896, 2019). "Some studies have shown that low concentrations of IL-1β promote the secretion of IL-17 from CD4+ T cells, inhibiting the body’s anti-tumor mechanisms." (PMID 31754923, 2019). "Similar expression patterns were seen for tumor-infiltrating CD4 T cells, but there was a higher frequency of Tregs expressing CTLA-4 compared with non-Treg CD4 T cells." (PMID 31804466, 2019). "IL-2, TNF-α, and IFN-γ immune factors enhanced the function of tumor-killing cells such as CD3+CD4+T and NK cells." (PMID 31256187, 2019). "Tumor-infiltrating CD4+ T cells showed a similar phenotype, indicating that rMVA-CD40L immunization promotes TIL expansion and reinvigoration." (PMID 31695037, 2019). "The tumor and its microenvironment are involved in the induction of activeTregs and contribute to the conversion of CD4+CD25-naïve T cells into CD4+CD25+ Treg cells." (PMID 31993233, 2019). "Here we showed that the treatment with LY364947 independent of the established subcutaneous KPC1 tumor decreases the relative amount of CD4+ T cells within the tumor microenvironment." (PMID 30959852, 2019). "Since regulatory T cells can also critically be affected by high salt and they greatly impact anti-tumor immunity, we also examined this suppressive CD4+ T cell subset thoroughly in our model." (PMID 31214164, 2019). "iTreg are derived from naïve CD4+ T cells in the periphery in response to tumor stimuli that drive differentiation toward a regulatory phenotype." (PMID 31681327, 2019). "According to these results, it has been previously shown that the transfer of low dose of CD4+ T-cells (5 × 104 cells per mouse) exerts a stronger effect than higher doses of CD4+ T-cells in an anti-tumour therapy." (PMID 31118938, 2019). "P2X7 pharmacological blockade does not replicate the immunosuppressive effects due to genetic ablation, rather it enhances tumor infiltration by CD4+ T effector cells and diminishes CD39 and CD73 expression, thus reducing immunosuppression in the TME." (PMID 30655604, 2019). "Malignant cells elimination by CD8+ CTLs has been considered for decades as a master regulator of anti-tumor immunity, confining CD4+ T cells to a supportive action." (PMID 31812953, 2019). "Our lab previously demonstrated the activity of anti-CTLA-4 in the Myc-Cap model and showed that CTLA-4 immunotherapy significantly increased the production IFN-γ by CD8 and CD4 tumor-infiltrating T cells." (PMID 31653272, 2019).
tumor (continued). "Further, combination treatment with the anti-CD4 mAb and immune checkpoint mAbs, particularly anti-PD-1 or anti-PD-L1 mAbs, synergistically suppressed tumor growth and greatly prolonged survival." (PMID 31340866, 2019). "Further to assess the effect of the DTT-neoAg vaccination on cellular immune composition of TILs, we measured the percentage of NK cells in the tumor tissues and FoxP3+/CD4+ ratio in the TILs." (PMID 31749795, 2019). "A large number of tumor-infiltrating lymphocytes (TILs) including CD4+ T cells in the tumor/liver interface and CD8+ T cells inside of the tumor have been demonstrated in HCC." (PMID 31231341, 2019). "On one hand, NK-cells prime dendritic cells, enhancing tumor antigen presentation to cytotoxic CD8+ T-cells and polarization of CD4+ T-cells towards an anti-tumor T-helper type 1 (Th1) phenotype." (PMID 30922362, 2019). "CCL20 assists tumor cells in immune evasion by increasing the migration of CD4+Foxp3+ Tregs towards tumor location." (PMID 31192256, 2019). "CD4+ T cells have been shown to elicit cytotoxicity and tumor rejection dependent on MHC class II-restricted recognition of tumors by tumor-reactive CD4+ T cells and participate in the anti-tumor immunity." (PMID 31780946, 2019). "TILs are polymorphic in nature and are predominantly found in the tumor microenvironment with CD4+, CD8+ T cells, B-cells, and NK cells." (PMID 31443339, 2019). "The results confirmed those from our previous study that durable anti-tumor immunity was mainly dependent on CD4+T cells." (PMID 30833570, 2019). "For neoantigen-based cancer vaccine, antigen-specific CD4+ T cell effectors can lead to tumor regression through direct cytotoxic mechanisms or activation of macrophages." (PMID 31749795, 2019). "In this study, we have revealed that TRAPs can educate CD4+ T cells to promote tumor growth and metastasis through an HSP90α–TLR2–IL-6–IL-10/IL-21 axis and the induction of IL-10+ Bregs." (PMID 31300052, 2019). "Treatment with anti-CTLA-4 antibody decreases tumor burden, Treg presence, and Treg to CD4+ and CD8+ ratios." (PMID 31681327, 2019). "The anti-PD-L1 Ab increased the percentages of tumor-infiltrating CD4+ and CD8+ T cells in mice vaccinated with an antigen-specific protein vaccine." (PMID 31546897, 2019). "Accompanied by the robust inflammatory responses followed by primary tumor destruction, CD4+CD8+ double positive T cells are highly boosted to harness host immunity to purge metastases in lymphoid organs." (PMID 30886812, 2019). "Modification of tumor cells by a low dose of NDV introduced T cell costimulatory activity and augmented in vivo tumor-specific T cell response as a result of CD4+ and CD8+ immune T cell cooperation." (PMID 31480379, 2019). "Consistently, inhibition of tumor autophagosome formation or IL-6 secretion by CD4+ T cells markedly retarded tumor growth." (PMID 31300052, 2019). "Immunization with recombinant adenovirus induced NY-BR-1-specific CTL as well as CD4+ T cell responses and reduced outgrowth of the NY-BR-1 expressing tumor cell line EONY#17 in DR4tg mice." (PMID 31519152, 2019). "To investigate the association between the enhanced liver injury and tumour‐induced inflammation in the AMPKα2 deficient mice, we analysed the proportions of CD3, CD3+/CD4+, CD3+/CD8+, F4/80+, NK1.1+ cells in the blood." (PMID 30636376, 2019). "For ACT of TILs, skewing toward CD8+ vs. CD4+ T cells is thought to provide better clinical outcome, as cytotoxic T cells are more reactive against the tumor." (PMID 31398192, 2019). "Consistent with this, tumor-derived and dLN-derived cDC2s stimulate CD4 T cells more efficiently, ex vivo, in Lewis lung carcinoma model expressing ova as a model antigen." (PMID 31143179, 2019). "CD4+ T-cells have been shown to recognize 5T4-derived antigens in human CRC patients and loss of this recognition has been linked with tumor progression." (PMID 31619516, 2019).
tumor (continued). "We also found that lactate enhances tryptophan metabolism and kynurenine production by pDCs which contribute to induction of FoxP3+ CD4+ regulatory T cells, the major immunosuppressive immune cell subset in tumor microenvironment." (PMID 31440253, 2019). "CD4+ cell depletion led to the proliferation of tumor-specific CD8+ T cells in the draining lymph node (dLN) and increased infiltration of PD-1+ CD8+ T cells into the tumor with a shift toward type I immunity within the tumor." (PMID 31340866, 2019). "This study demonstrates repolarization of M2-like PECs upon MHC II-restricted interaction with tumor specific CD4+ Th1 cells in vitro as shown by extensive gene and protein expression analyses." (PMID 30853959, 2019). "Treatment with CAELYX® alone reduced the amount of CD4+ T cells in the tumor microenvironment on day 13 and 14, as demonstrated by both IHC and flow cytometry (respectively)." (PMID 30670061, 2019). "Dissemination of tumor antigen-associated (TAA) CD8+ T cells with IT IL-12 have been reported and depletion of CD8+ T cells diminished IL-12 antitumor effects, whereas CD4+ or NK depletion had a modest effect." (PMID 30323352, 2019). "Analysis of TILs performed on explanted tumors 4 days post adoptive T cell transfer revealed that on average 2.7 × 104 OT-II cells had reached the tumor, representing 19.3% of the CD4+ TIL compartment in B16F10/M2KO/OVA tumors." (PMID 30853959, 2019). "We thus assume that the differentiation of TAMs selectively observed in OVA expressing B16F10/M2KO/OVA tumors was caused by IFNγ released from CD4+ Th1 cells as a consequence of tumor antigen-specific TAM / CD4+ Th1 interaction in vivo." (PMID 30853959, 2019). "In summary, the induction of a polyclonal CD4+ T cell response indicates activation of a diverse repertoire of CD4+ T cells and suggests T cell reactivity against multiple tumor (neo)antigens." (PMID 30956760, 2019). "This is also observed in tumors, where tumor antigen specific CD4+ T cells in the tumor draining lymph node (TDLN) are activated, but diverted either into anergy or Treg formation, which is enhanced by already present Tregs in the TDLN." (PMID 30842776, 2019). "Further, studies in mice have shown that CD4+ T cells are required for inducing CD8+ anti-tumor responses 6,7." (PMID 31754392, 2019). "To investigate T cell subsets in three different tumor specimens, we compared the ratio of CD4+ and CD8+ T cells in PBLs, EILs, and TILs isolated from PB, ME, and TM, respectively." (PMID 31801611, 2019). "We found that the frequency of CD4+Foxp3+ Tregs was increased in circulating and tumor-infiltrating lymphocytes from BC patients." (PMID 30718502, 2019). "TIM-3 is an inhibitory receptor and a surface protein that is selectively expressed on CD4 + T-helper 1 and CD8+ T cytotoxic cells that causes T cell failure in tumour progression and chronic virus infection." (PMID 30777100, 2019). "Specifically, CD11b+CD103− DC predominate in PDA, express high IL-23 and TGF-β, and induce FoxP3neg tumor-promoting IL-10+IL-17+IFNγ+ regulatory CD4+ T cells." (PMID 30926808, 2019). "First, we isolated tumor infiltrated Gr1+ cells (including Gr1highLy6G+ and Gr1dimLy6G− populations) and found that these cells inhibited the proliferation of CD4+ and CD8+ T cells in vitro, an important functional characteristic of MDSCs39." (PMID 31444334, 2019). "As such, promoting CD4+ responses to tumors and the generation of CD4+ T cell memory are crucial to developing an effective anti-tumor immune response." (PMID 31379821, 2019). "Our study provides a proof-of-concept methodology to characterize tumor-specific CD4+ T cell effector programs." (PMID 31801070, 2019). "In this study, we show that human CD4+ TEMs stimulated with CD28SA adopt a metabolic program similar to those of tumor cells with enhanced glucose utilization, lipid biosynthesis, and proliferation in hypoxic conditions." (PMID 31009338, 2019).
tumor (continued). "Although in vitro cytotoxic activity of CD4+ T cells was weaker than CD8+ T cells, in vivo anti-tumor activity of CD4+ T cells was similar to CD8+ T cells." (PMID 30626427, 2019). "CD4+ T cells are skewed toward T helper cell subsets and support the anti-tumor immune response by the release of cytokines or tumor cell killing." (PMID 31040852, 2019). "This indicates a strong T cell expansion or maintenance after chemotherapy, especially of CD4+ T helper cells that are nevertheless unable to control tumor growth in these tumor patients." (PMID 30740106, 2019). "We found that the protective effect of cryoablation treatment against an abscopal tumor is mediated by an increase in the numbers of CD4+ T cells, CD8+ T cells, the Th1/Th2 ratio, and the killing activity of CTLs and NK cells." (PMID 31289616, 2019). "CD4+ T cells interact with tumor cells through CD40L, CD80, and CD54 and protect them from cytotoxic T cells and natural killer (NK) cells." (PMID 31096713, 2019). "Obesity correlated with better response to PD-1/PD-L1 blockade in tumor-bearing mice, as demonstrated by an increase in TILs and CD8+/CD4+ ratio, reduction in tumor burden and metastases, and improved survival." (PMID 31475003, 2019). "Varying degree of lymphocyte infiltration was observed and tumor types were stratified into immunologically “hot” or “cold” tumors based on their numbers of CD4+ and CD8a+ cells 12,30-32." (PMID 31754392, 2019). "cDC2s were shown to drive CD4+ anti-tumour immunity in a B16-F10 melanoma model after depletion of regulatory T cells (Tregs), which suppress cDC2 migration and function." (PMID 31776331, 2019). "In particular, vaccine-induced CD4 T cells promote an inflammatory tumor microenvironment, by producing IFNg, which improves CTL killing activity and sensitizes tumor cells for recognition and direct killing by cytotoxic Th1 effectors." (PMID 31291991, 2019). "As the antitumor effect of BCG-CWS was known to be mediated by the activation of the immune system and the induction of an inflammatory response, IL-6 production, and CD4 infiltration were evaluated by IHC after tumor tissues were harvested." (PMID 31817179, 2019). "In radiofrequency ablation-treated tumors of CCR1 deficient mice the loss of CCR1 affects the accumulation of CD11C+, CD4+, and CD8+ T cells in the tumor." (PMID 31311583, 2019). "This was associated with the increase of activated anti-tumoral CD4+ and CD8+ T cells and the decrease of Treg cells in the tumor microenvironment." (PMID 31320999, 2019). "With respect to their anti-tumor activities, it has been shown that murine DN (CD4−) iNKT cells, particularly from the liver, have higher lytic activity than their CD4+ counterparts." (PMID 31569599, 2019). "The immune tumor microenvironment of patient 3 consisted of mainly central memory CD4+ and CD8+ T cells, and Tregs." (PMID 31395100, 2019). "Analysis of the TCR-Vβ-repertoire showed that a polyclonal T cell response was induced, suggesting the capacity of vaccine-activated CD4+ T cells to target multiple tumor (neo)antigens." (PMID 30956760, 2019). "The proportion of CD4+ Tregs to total CD4+ in the tumor microenvironment of syngeneic tumors however, has been reported to ~ 0.5-8% 54,56." (PMID 31754392, 2019). "While the percentage of CD4+ cells that were Th1 remained stable throughout the tumor, tumor periphery, and healthy pancreas, Th2 and Treg cells were more likely to be in the central tumor, whereas Th17 cells were more likely to be in the healthy pancreas." (PMID 30931508, 2019). "Associations with clinical outcomes were stronger with polyfunctional CD4+ T cells compared with CD8+ T cells, and anti-tumor efficacy associated with polyfunctional IL-17A-producing T cells." (PMID 31775882, 2019). "Conversely, CD4+ T cells can also gain tumor protective function as CD4+ T cells with cytotoxic capacity were shown to eliminate MHC II expressing tumor cells." (PMID 30853959, 2019).
tumor (continued). "We found that the CD4+ T cell population in the primary tumor was more abundant after CPMV monotherapy or combination therapy compared to the PBS group, with CPMV monotherapy achieving a more significant increase." (PMID 31453050, 2019). "In-depth phenotypic characterisation of immune responses showed that tumour-reactive CD4+ T cells frequently infiltrate OC." (PMID 30718808, 2019). "Beyond their role in antigen cross-presentation, cDC1s are the major source of IL-12 production and thus influence anti-tumor immunity by activating NK cells and driving CD4 T cell responses toward Th1 responses." (PMID 31143179, 2019). "HSP90α on the surface of TRAPs programs the immunosuppressive functions of CD4+ T cells to promote tumor growth and metastasis." (PMID 31300052, 2019). "Among the different TIL subsets, CD4+ or CD8+ T lymphocytes can recognize tumor antigens or eliminate tumor cells." (PMID 31214035, 2019). "We observed a significant decrease in the incidence of CD4+FoxP3+T cells in treated tumor tissue (F = 7.567, DF = 5, by ANOVA with Sidak’s posttest; p < 0.0001)." (PMID 31462642, 2019). "In HFD-mice, the infiltration and activation of immune cells into tumor-sentinel lymph nodes was overall reduced, except for activated CD4+ T cells expressing low CD25 levels." (PMID 31616626, 2019). "CD4+ Th recognize tumor antigens that can assist CD8+ T cells, macrophages to phagocytose tumor cells, and B cells to produce antibodies against tumor cells." (PMID 31450710, 2019). "Tumor samples from HPK1 KD mice demonstrated significantly upregulated key immune cell markers involved in mediating anti-tumor immunity, including CD4, CD8, IFNγ, TNFα, Granzyme B, CD28, CD11c and CD11b." (PMID 30913212, 2019). "TGF-β1 is produced by multiple cell types within the tumor microenvironment, whereas IL-10 production appears to be restricted to CD4+ T cells." (PMID 31775909, 2019). "We demonstrated that the amount of CD4+CD28− cells is lower in fully recovered mice in comparison with tumor-free and tumor-bearing mice." (PMID 31717542, 2019). "Conversely, inactivated CD8+CD25− and CD4+CD25+FOXP3+ Treg cells were found within the tumor tissue." (PMID 30987226, 2019). "Purified Treg cells (CD4+CD25+) from spleen of tumor-bearing mice (Treg STB) or tumor (Treg PTB) were co-cultured with tumoral MDSCs." (PMID 32038621, 2019). "Because many tumors express PD-L1, the rationale of PD-L1 pathway blockade is to inhibit the immunosuppressive PD-L1/PD-1 interaction between tumor cells and T cells that hampers the activity of CD4+ and CD8+ T cells." (PMID 31244860, 2019). "High pre-treatment tumor CD4+ T cell content is the only parameter, apart from high TML, that associates with immunotherapy responses in two of the panel of six SCC tumor lines studied here." (PMID 30832732, 2019). "MHC-II expression is required for CD4+ T cell anti-tumor responses, and loss of MHC-II is associated with aggressiveness of colorectal cancer and decreased levels of tumor-infiltrating lymphocytes." (PMID 31627281, 2019). "This was our first goal, and the results are encouraging, with 6 out of 20 patients responding to treatment, mainly by recruiting CD4+ cells to the tumor site." (PMID 31849934, 2019). "Recruitment of CCR7+ lymphoid tissue inducer (LTi) cells by CCL21-expressing melanomas leads to TLO formation, which also recruit immune suppressive cells like CD4+ Treg cells and MDSCs to suppress anti-tumor immune response." (PMID 31281318, 2019). "Despite CD8+ T cell responses against tumor cells are well-understood, information about the role of CD4+ T cell immunity in cancer is limited." (PMID 31555274, 2019). "Mice lacking H4R show reduced tumour size and weight, decreased number of lung metastases and percentage of CD4+ tumour-infiltrating T cells, while exhibiting increased infiltration of NK cells and CD19+ lymphocytes." (PMID 29988113, 2019).